EPCAM (epithelial cell adhesion molecule)
Diseases named in the same sentence as EPCAM in open-access papers (continued):
Sharing a sentence is not in itself a finding about the gene and the disease.
infection (continued). "Analyses of earlier time points (3 and 9 dpi) demonstrated a stepwise increase in the number of HER2+ cells and Ki67+ HER2+ cells after MA10 infection, with transient increases in EpCAM positivity and reductions in vimentin positivity, as observed after IAV infection." (PMID 40739350, 2025). "To identify the targets of WNV infection in the culture, we stained enteroid monolayers with Abs against WNV and different cell markers, and found that WNV infects villin- and EpCAM-expressing epithelial cells in STAT1-deficient monolayers, compared to limited infection in wild-type enteroids." (PMID 37749080, 2023). "HER2, EpCAM, and MSLN CAR-T cells were prepared through lentiviral infection of peripheral blood mononuclear cells." (PMID 38702509, 2024). "Lung from one animal was harvested 7 days after intranasal infection, stained for fungi, and counterstained with CD31 + Pdx to label blood vessels, and with epithelial cell adhesion molecule (EpCAM) to label airway epithelium." (PMID 38511961, 2024). "The infection efficiency was evaluated using flow cytometry using anti-HER2, anti-EpCAM, and anti-MSLN antibodies." (PMID 38702509, 2024). "An Il23aVenus strain reveals the EpCAM+ DCIR2+ cDC2s as a key cellular source of IL-23 at steady state and during infection with Citrobacter rodentium." (PMID 38180443, 2024). "We compared the infection of R26-LSL-Tomato (Tom) mice with 2 × 108–109 plaque-forming units (PFU) of Ad-CMV-Cre or Ad-SPC-Cre and analyzed expression of CD45 and EPCAM on tomato+ cells in the lung." (PMID 34632444, 2021). "As with Ad-CMV-GFP, Ad-CMV-Cre showed infection of a majority CD45+ (54%) cells and 39% EPCAM cells, but by contrast, ∼27% of the tomato+ cells in Ad-SPC-Cre-infected mice were EPCAM+, while only 37% were CD45+, with fewer cells expressing tomato overall." (PMID 34632444, 2021). "At 48 hr post infection, we harvested small intestines, isolated crude IECs, and sorted for CD26+EpCAM+CD44-CD45- mature villous IECs, the primary target cells of RV in the gut." (PMID 30460894, 2018). "Despite equal multiplicities of infection (MOI = 100) used for all transfections, EpCAM overexpression was stronger in polarized cells than in standard culture conditions." (PMID 23758908, 2013). "We found a variety of ISM1+-expressing cells, including CD45+ cells, EpCAM+ cells, and, importantly, we also found different subsets of cells carrying hematopoietic stem cell markers (LSKs) expressing ISM1, and their frequency was perturbed during infection." (PMID 40572169, 2025). "We examined the cell death in CD45-CD31-Tie2- EpCAM+ epithelial cells and CD45- CD31- Tie2- EpCAM-PDGFRα+ fibroblasts in the skin tissue of C. auris-infected WT and Ifng-/- mice after 5 days post-secondary infection." (PMID 40294061, 2025). "Age > 60, a clinical factor associated with the TLT subtype, was associated with 57 upregulated genes, including BCR signaling genes, IL6 (related to infection), and IL21R (different from TLT vs. ME), and 141 downregulated genes including EPCAM, AR, WT1, and CD28." (PMID 39866884, 2025). "We found that neither EpCAM− CD45+ nor EpCAM+ CD45+ (including resident γδ T) cells stained for the presence of IFN-γ 4d post-infection." (PMID 38543790, 2024). "TMPRSS10 protein expression was observed on the apical membrane of LTL+/EpCAM + PTs within enhanced kidney organoids, with the presence of viral RNA (dsRNA) within TMPRSS10-expressing PTs confirmed at 6 days post-infection." (PMID 38334329, 2024). "Infection with 5 MOI of EpCAM-WT lentiviral particles did not affect E-cadherin expression; however, dose dependent treatments of 2, 5, and 10 MOI of EpCAM-L240A lentiviral particles induced ZEB1 and vimentin expression and suppressed E-cadherin expression." (PMID 37192201, 2023).
infection (continued). "Using a multiplicity of infection (MOI) of 100 viruses/cell we obtained a strong EpCAM expression in HMECs without any effects on cell viability." (PMID 23758908, 2013). "Within infected SGs, CD200+ cells were predominantly large CD31+ cells (isotype controls:S1A Fig.) that were EpCAM-, suggestive of endothelial cell origin, and not EpCAM+ acinar epithelial cells in which MCMV replicates during the persistent phase of infection." (PMID 25654642, 2015).
gastrointestinal tumors (18 papers, 2007 to 2025). "IMC001, an anti-EpCAM CAR-T therapy, as monotherapy or in combination with immune checkpoint inhibitors, is currently in Phase I and II trials for EpCAM+ tumors of the digestive system (NCT05028933, NCT04196465)." (PMID 38612911, 2024). "In this way, in a study including 35 patients with 11 different gastrointestinal tumors, the authors isolated CTCs with an EpCAM‐positive enrichment method, quantified PD‐L1 levels on CTCs, and only examined the distribution of PD‐L1high CTCs." (PMID 36177552, 2023). "Only 2% to 3% of all LS cases are due to deletions of the 3′-end of the epithelial cell adhesion molecule (EPCAM) gene and present almost exclusively with gastrointestinal (GI) tumors, predominantly CRC." (PMID 33003511, 2020). "It rapidly emerged as an attractive target for specific immunologic approaches and the first monoclonal antibody that was ever used in patients with gastrointestinal tumours three decades ago was the EpCAM-directed monoclonal antibody 17-1A." (PMID 26296970, 2015). "The discovery that the pan-epithelial homotypic cell adhesion molecule EpCAM is differentially expressed on gastrointestinal tumours has made this a viable target for immunotherapy." (PMID 17325709, 2007). "The temporal expression of EpCAM in the life cycle of human gastrointestinal tumours remains largely unstudied." (PMID 17325709, 2007). "Similarly, the metastasizing gastrointestinal tumours frequently expressed a complex composed of the tetraspanin D6.1A and CD44v6, EpCAM, claudin-7." (PMID 32091301, 2020). "The expression of EpCAM was related to a worse OS in gastrointestinal tumors and a worse DFS in gastrointestinal tumors and head and neck tumors." (PMID 37664060, 2023). "Next, the first-in-human, open-label, multi-centers trial (NCT05028933) in patients with EpCAM- positive relapsed/ refractory gastrointestinal (GI) tumors was designed to examine the safety, efficacy and cytokinetic profile of IMC001, an EpCAM- specific CAR-T cell based immunotherapy." (PMID 36564524, 2023).
colorectal (15 papers, 2008 to 2025). "Before usage in the clearing and immunolabelling protocol, EpCAM labelling was validated on murine colorectal liver metastases immunohistochemistry (IHC) sections." (PMID 37077833, 2023). "Consequently, we selected eight statistically significant TACTs—EPCAM, KRT19, ERBB2, MKI67, MCAM, FOXA2, SNAI2, and NPTN—which we designated as colorectal TACTs (C-TACTs)." (PMID 40003943, 2025).
epithelial neoplasm (5 papers, 2015 to 2025). A benign or malignant neoplasm that arises from and is composed of epithelial cells. "Epithelial cell adhesion molecule (EpCAM) is a type I transmembrane glycoprotein overexpressed in human epithelioma but with relatively low expression in normal epithelial tissues." (PMID 25960617, 2015). "As a result, most epithelial neoplasms show increased EpCAM expression." (PMID 37627911, 2023). "Although many epithelial neoplasms stained with both antibodies, the fraction of positive cases was often lower for TROP2 than for EpCAM." (PMID 38786342, 2024).
colon polyps (4 papers, 2017 to 2023). "Results reveal that expression of EpCAM and PD-L1 on CD4+ T cells significantly increased in patients with CC, compared with age- and sex- matching healthy controls and patients with colonic polyps." (PMID 31354723, 2019). "To verify whether the identified population EpCAM+ CD4+ T cells increased in patients with benign polyps, we examine a cohort of patients with colonic polyps (CP) and determine their T cell subset landscape using the same mass cytometry staining panel above." (PMID 31354723, 2019). "Inspired by the characterization of cellular defects in a rare EpCAM-related human intestinal disease, we find that the absence of EpCAM in enterocytes results in an aberrant apical domain." (PMID 28084299, 2017).
benign tumors (3 papers, 2019 to 2022). "In a more recent series of 87 patients with indeterminate adnexal masses, CTCs enrichment and detection (using physical properties of CTCs and CD45/CK/EpCAM immunostainings) was able to discriminate benign tumors from OvC with a 77.4% sensitivity and 100% specificity." (PMID 31167492, 2019).
head and neck tumors (2 papers, 2018 to 2023). "The DFS of head and neck tumors (HR: 2.33, 95% CI: 1.51-3.61, P < 0.01) was also associated with the overexpression of EpCAM." (PMID 37664060, 2023).
immune dysfunction (2 papers, 2020 to 2021). "EVs expressing CD63 and EpCAM (Epithelial cell adhesion molecule) suppress DC maturation and inhibit antigen presentation by DCs and also induce DC apoptosis in post-trauma immune dysfunction in rats." (PMID 34177577, 2021).
brain disorder (1 paper, 2022). A disease affecting the brain or part of the brain. "Aptamers can also be fused together, such a bifunctional aptamer targeting the transferrin receptor and the epithelial cell adhesion molecule (EpCAM) has demonstrated proof-of-concept that such RNA aptamers can overcome the BBB to target brain disorders." (PMID 35067193, 2022).
CNS tumors (1 paper, 2015). "In CNS malignancies, one of the main challenges is finding a suitable biomarker for identification of these cells, because automated systems, such as the widely used Cell Search system, are reliant on markers, such as the epithelial cell adhesion molecule, which are not present in CNS tumors." (PMID 26322014, 2015). "In CNS malignancies, one of the main challenges is finding a suitable biomarker for identification of these cells, because automated systems, such as the widely used Cell Search system, are reliant on markers, such as EpCAM, which are not present in CNS tumors." (PMID 26322014, 2015).
hematological neoplasms (1 paper, 2024). "It is of note that some EpCAM positivity could also be observed in several mesenchymal and hematological neoplasms." (PMID 38786342, 2024).
inflammation (1 paper, 2023). Aberrant reaction of the microcirculation characterized by movement of fluid and leukocytes from the blood into extravascular tissues. "It was also demonstrated that alveolar EpCAM expression in normal lung tissues results in the recruitment of EpCAM-redirected CAR-Ts and their activation in the mentioned sites leading to CAR-T-mediated lung inflammation and tissue damage." (PMID 38146364, 2023).
EPCAM also shares sentences with these, for which no sentence is quoted: basal cell carcinoma (16 papers); Familial adenomatous polyposis (7); multiple myeloma (5); genetic disorder (4); soft tissue tumors (4); adrenal carcinoma (3); autosomal dominant inherited disorder (3); Cowden Syndrome (3); hematological malignancies (3); hereditary cancer syndrome (3); hereditary colorectal cancer (3); Hodgkins lymphoma (3); metastasis (3); microcystic adnexal carcinoma (3); Obesity (3); ovarian epithelial tumor (3); rhabdomyosarcoma (3); tufting enteropathy (3); undifferentiated carcinoma (3); Alzheimer disease (2); basal cell carcinomas of the skin (2); breast/ovarian cancer (2); carcinoma in situ (2); cervical adenosquamous carcinoma (2); eccrine porocarcinoma (2); Ewing sarcoma (2); fibrosarcoma (2); hemophilia A (2); hypopharyngeal cancer (2); intrahepatic cholangiocarcinoma (2).
A further 142 diseases each share a sentence with EPCAM in 2 papers or fewer.